CHEK2 (checkpoint kinase 2)
Diseases named in the same sentence as CHEK2 in open-access papers (continued):
Sharing a sentence is not in itself a finding about the gene and the disease.
breast cancer (continued). "Higher frequencies, 5.1–11.4%, of the CHEK2 1100delC allele have by some investigators been reported in non-BRCA1/2 families with hereditary breast cancer, although other studies from e.g. Australia and Spain have not found an increased frequency in such families." (PMID 16539695, 2006). "Mutations in the CHEK2 gene have been found in patients with Li-Fraumeni syndrome and one such mutation – the rare 1100delC gene mutation – has been found to increase breast cancer susceptibility at the population level and in families without BRCA1 or BRCA2 gene mutations." (PMID 17132159, 2006). "Both families that carried the CHEK2 1100delC variant contained cases of bilateral breast cancer." (PMID 15700044, 2005). "The increased breast cancer risk associated with CHEK2 1100delC may therefore be attributed to a threshold level of phosphorylation of CHK2 below which cells become more susceptible to other genetic and environmental factors promoting tumorigenesis." (PMID 15700044, 2005). "Such compensation of the 1100delC defect in CHEK2 might explain the rather low breast cancer risk associated with the CHEK2 variant, compared to that associated with truncating mutations in BRCA1 or BRCA2." (PMID 15700044, 2005). "To investigate if variants of CHEK2 other than 1100delC confer an increased risk of breast cancer, we have screened a series of 68 familial breast cancer cases, which had been screened in the Regional Genetics Service and found to be negative for mutations in BRCA1 and BRCA2." (PMID 12454775, 2002). "On the assumption that they have pathogenic potential, variations in CHEK2 may account for around 7% (95%; CI: 2–16%) of familial breast cancer cases." (PMID 12454775, 2002). "Our present investigation suggests that a few rare variants in CHEK2 may confer an increased susceptibility to breast cancer." (PMID 12454775, 2002). "On the assumption that all the variants we have identified have pathogenic potential then variation in CHEK2 might account for 7% (95% CI indicate up to 16%) of familial breast cancer." (PMID 12454775, 2002). "Although CHEK2 pathogenic variants are considered moderate-risk factors in breast cancer, the fact that it is so frequently found in breast cancer patients hypothesizes that there are other potentiating risk factors of the same molecular pathways or alternative pathways." (PMID 40507526, 2025). "Thus, MHT after natural menopause (as was studied in WHI) may be a clinically relevant option for ATM or CHEK2 PV carriers, and its potential impact on breast cancer risk should be further studied." (PMID 40298171, 2025). "Indeed, women with CHEK2 mutations have a 28%–37% lifetime risk of developing breast cancer." (PMID 38313678, 2024). "The likelihood of a variant being reported was similar between the two classification systems with 3 exceptions: The breast cancer-associated CHEK2 Ile200Thr variant was more likely to be reported after ABC classification (91%) than after ACMG classification (83% when including maybes)." (PMID 38778080, 2024). "Although CHEK2 founder mutations c.1100delC (p.Thr367Metfs∗15) and c.470T>C (p.Ile157Thr) have been shown to increase breast cancer risk by 2.6- and 1.4-fold, respectively, the extent to which the vast majority of CHEK2 variants are associated with elevated risk remains unclear." (PMID 39642869, 2024). "In the currently analyzed cohorts, CHEK2 p.(Asp438Tyr) carriers were identified in 0.7% of the cases with the indication of hereditary predisposition to disease and with similar frequency (0.6%) in the breast cancer cases unselected for family history or age at disease onset." (PMID 36653541, 2023). "Interestingly, 6 of the 7 women with two CHEK2 variants had bilateral breast cancer." (PMID 37563628, 2023).
breast cancer (continued). "To test whether the association of CHEK2 mutation with poor outcome observed in breast cancer extends to other cancer types preferentially in women, we conducted a gender-stratified Kaplan-Meier analysis of disease-specific survival and somatic mutations in ATM and CHEK2 across solid cancers." (PMID 37390209, 2023). "Additionally, variants of unknown/uncertain significance (VUS) in breast cancer susceptibility genes CHEK2, BRCA2 and BRIP1 were determined to be present in three different PABC patients (15%)." (PMID 34011307, 2021). "Furthermore, it is likely that the presence of pathogenic variants in the CHEK2 gene will impact management options for those in whom detection coincides with the diagnosis of breast cancer, in consideration of targeted chemotherapy and the safety of radiotherapy." (PMID 33803639, 2021). "It is accepted practice that the carriers of truncating variants in CHEK2 are offered at least “moderate” risk screening, with annual mammograms starting from the age of 40 and continuing until the age of 50, with screening thereafter as part of the national breast cancer screening programme." (PMID 34771713, 2021). "Furthermore, mutations in moderate-penetrance genes such as BRCA1 interacting protein C-terminal helicase 1 (BRIP1), ataxia telangiectasia mutated (ATM), partner and localizer of BRCA2 (PALB2), and checkpoint kinase 2 (CHEK2) are associated with a two-fold increased risk of developing breast cancer." (PMID 33027908, 2020). "Moreover, empiric risk estimates based on family history of breast cancer may mirror the magnitude of CHEK2-associated risk in breast cancer families found to have a mutation." (PMID 26484312, 2015). "However, this widely discussed variant of CHEK2 – which seemed clearly associated with the predominance of breast cancer in western countries – was rarely detected in Asian populations, such as the Chinese, Koreans, Japanese, Singaporeans, Malaysians and South Indians." (PMID 25674498, 2015). "Likewise, several previous studies have suggested that CHEK2 I157T variant may contribute to inherited breast cancer predisposition." (PMID 25674498, 2015). "Mutations in the CHEK2 gene, including truncation variant 1100delC, have been reported to increase breast cancer risk by up to two-fold and may vary according to the Li-Fraumeni syndrome as well as breast cancer." (PMID 22736197, 2012). "Finally, the CHEK2 gene has been associated with several types of cancer, including breast cancer." (PMID 20548946, 2010). "However, it is still possible that BCoR-L1 could be involved in breast cancer predisposition as a moderate- or low-penetrance risk gene, as has been found with CHEK2, BRIP1, and PALB2 in large studies of BRCAX cases and controls." (PMID 17697391, 2007). "The 5-year cumulative risk (CR) of contralateral breast cancer (CBC) was 0.55 for BRCA1/2, 0.89 for ATM, and 0.80 for CHEK2 carriers." (PMID 41976331, 2026). "Genetic testing revealed a pathogenic CHEK2 nonsense variant (p.Trp411*), a likely pathogenic MSH6 frameshift variant, and a breast cancer PRS in the 99th percentile." (PMID 41919251, 2026). "Beyond the high-penetrance genes associated with breast cancer, moderate-risk genes, such as ATM, BARD1, and CHEK2, also contribute to hereditary breast cancer predisposition and are therefore considered part of the HBOC spectrum." (PMID 41528496, 2026). "We focused on Polish founder mutations in BRCA1, BRCA2, PALB2, CHEK2, NBN and RECQL (18 alleles), which account for one-half of Polish breast cancer families." (PMID 40770660, 2025).
breast cancer (continued). "This is in parallel with variants in genes implicated in hereditary breast cancer including the ‘high risk’ genes BRCA1, BRCA2, and PALB2 and ‘moderate risk’ genes CHEK2 and ATM." (PMID 41327266, 2025). "Research on the potential interaction of modern MHT regimens with breast cancer risk due to PVs in ATM, CHEK2, and other genes should be prioritized." (PMID 40298171, 2025). "Case #10 with P/LP variants in CHEK2 and SDHAF2 variants had a mixed phenotype with endometrial and breast cancer." (PMID 40943312, 2025). "We report on penetrance and breast cancer risk–modifying factors for PVs in BRCA1/2, ATM, CHEK2, and PALB2 among WHI participants." (PMID 40298171, 2025). "Most breast cancer susceptibility genes are involved in the damage repair signaling pathway, i.e., including BRCA1, BRCA2, PALB2, CHEK2, ATM, BARD1, RAD51C, and RAD51D." (PMID 40649769, 2025). "For the BRCA1, BRCA2, PALB2, CHEK2, and ATM genes, most protein-truncating variants have been associated with a high risk of breast cancer." (PMID 39858629, 2025). "We characterized breast cancer risk associated with established risk factors among WHI participants who carry PVs in BRCA1/2, ATM, CHEK2, and PALB2." (PMID 40298171, 2025). "It is also the first study that established risk estimates for recurrent disease-free survival and distant disease-free survival in ER-positive CHEK2 c.1100delC breast cancer patients." (PMID 41314031, 2025). "This preliminary study investigated the distribution and potential associations between three DNA repair gene polymorphisms—XRCC1 (rs1799782), CHEK2 (rs17879961), and XPD (rs238406)—in a cohort of female patients diagnosed with breast cancer." (PMID 40507526, 2025). "The analysis aimed to explore the distribution of XRCC1 (rs1799782), CHEK2 (rs17879961), and XPD (rs238406) genotypes in a cohort of female breast cancer patients and their potential association with clinical characteristics and histopathological subtypes." (PMID 40507526, 2025). "Furthermore, if a mutation is found (i.e. in BRCA1/2 or CHEK2) then specific surveillance protocols may be recommended for the mutation carriers (usually for breast and other cancers, because most breast cancer susceptibility genes are associated with a multi-site cancer predisposition)." (PMID 40770660, 2025). "While there is a need for prospective data collection to answer questions on prognosis after breast cancer occurrence in CHEK2 c.1100delC heterozygotes, a first step would be to study the prognosis in a recent cohort." (PMID 41314031, 2025). "An analysis used breast cancer microsimulation models from the Cancer Intervention and Surveillance Modeling Network to compare different screening strategies for ATM, CHEK2, or PALB2 P/LP variant carriers." (PMID 39858629, 2025). "We selected all breast cancer patients who were identified within the Hebon-CHEK2 study, a nationwide study on hereditary breast and ovarian cancer with a special focus on CHEK2 c.1100delC families." (PMID 41314031, 2025). "Deactivating variants are less similar; for example, p.His371Tyr two positions N-terminal in CHEK2 in breast cancer and the equivalent N-terminal position p.Leu597Val in BRAF was shown to be activating." (PMID 41152984, 2025). "Polymorphisms in repair genes (BRCA1, BRCA2, CHEK2, XRCC1, XPD) can reduce DNA repair efficiency, leading to genomic instability and increased breast cancer risk." (PMID 40507526, 2025).
breast cancer (continued). "Of the 143 patients, 24 (16.8%) had a PGV in a breast cancer susceptibility gene (BRCA1, n = 17; BRCA2, n = 5; PALB2, n = 1; CHEK2, n = 1)." (PMID 39964682, 2025). "The Breast Cancer Association Consortium reported the risk of 2.2 for DCIS in association with CHEK2 truncating variants, 0.8% of 4187 DCIS patients carried a CHEK2 truncating mutation." (PMID 40770660, 2025). "A strong association between the risk of breast cancer and family history was found for ATM, BRCA1, BRCA2, CHEK2, and PALB2 P/LP variant carriers." (PMID 39858629, 2025). "Twenty-four individuals (16.8% [95% CI, 11.1%-23.9%]) with germline testing had PGVs in breast cancer susceptibility genes, including BRCA1 (n = 17 [70.8%]), BRCA2 (n = 5 [20.8%]), PALB2 (n = 1 [4.2%]), and CHEK2 (n = 1 [4.2%])." (PMID 39964682, 2025). "A similar calculation for breast cancer was conducted by using BRCA1/2 as high-risk genes and CHEK2, ATM and PALB2 for intermediary risk genes." (PMID 40016794, 2025). "Based on the current study, women with a CHEK2 mutation face an increased risk of DCIS, in particular in the presence of a positive family history of breast cancer." (PMID 40770660, 2025). "The risk associated with breast cancer for P/LP variants in PALB2 varied between moderate and high (OR 3.83–5.02), whereas those in CHEK2 and ATM were associated with moderate risk (OR 2.54–2.47 and OR 1.82–2.10, respectively)." (PMID 39858629, 2025). "Protein-truncating variants in established susceptibility genes BRCA2, BRCA1, CHEK2, PALB2, ATM and MAP3K1 were associated with a risk of breast cancer, while BARD1 and ATRIP met exome-wide significance for the first time." (PMID 41044259, 2025). "In the CHEK2 p.I157T group, the frequency of breast cancer was 9% (4/44) and prostate cancer 11% (5/44)." (PMID 40335619, 2025). "The GEN1 gene is implicated in DNA damage repair, as are several high- or moderate-risk breast cancer susceptibility genes, i.e., BRCA1, BRCA2, PALB2, CHEK2, ATM, and BRIP1." (PMID 40649769, 2025). "In PTV meta-analyses including FinnGen10, the BRCA2 association was attenuated, but CHEK2 and PALB2 were more strongly associated with breast cancer." (PMID 41044259, 2025). "Previous studies have consistently reported a worse prognosis for CHEK2 c.1100delC breast cancer patients and a higher incidence of recurrent disease and distant metastatic disease than non-carriers." (PMID 41314031, 2025). "Pathogenic/likely pathogenic variants in the BRCA1 gene were found more often in patients with ER-negative BC compared to ER-positive BC (10.9% vs. 4.2%, p < 0.001), while P/LP variants in CHEK2 were exclusively identified in BC patients with ER-positive breast cancer (3.4% vs. 0%, p < 0.001)." (PMID 39684352, 2024). "In this study, it was also found that the decrease in mRNA levels for several other key DNA repair proteins, including BRCA2 (Breast Cancer Gene 2), CHK1 (Checkpoint kinase 1), CHK2 (Checkpoint kinase 2), Rad51, and ATR, was caused by long-term exposure to Al." (PMID 39795956, 2024). "Recent comprehensive studies have highlighted that pathogenic variants (PVs) across eight distinct genes, such as ATM, BRCA1, BRCA2, CHEK2, PALB2 (FANCN), RAD51C, and RAD51D, exhibit a substantial correlation with breast cancer risk." (PMID 38397209, 2024). "CPM decisions are also frequently observed in patients with ATM, CHEK2, and PALB2, which are the three most common moderate-risk breast cancer genes." (PMID 39335183, 2024). "Variants involving ATM, CHEK2, BRIP1, RAD51C, RAD51D, NBN and BARD1 are known to be associated with a moderately increased risk of breast cancer and a lifetime risk of around 25%." (PMID 38439815, 2024).
breast cancer (continued). "The frequency of P/LPs in CHEK2 in the Carriers study, which included a large cohort of patients with breast cancer, was 1%." (PMID 39594831, 2024). "Our findings inform clinical care by supporting current recommendations for prostate and breast cancer surveillance and provide definitive evidence of increased risk for renal, bladder, and CLL in heterozygotes with pathogenic CHEK2 variants." (PMID 39371170, 2024). "Despite being considered a tumor suppressor gene in colorectal and breast cancer, CHEK2 can paradoxically function as a potential oncogene in HCC, as our research findings suggest." (PMID 38242891, 2024). "Besides BC, CHEK2 pathogenic variants have been linked to various tumor types, including colorectal cancer, prostate cancer, renal cell carcinoma, thyroid cancer, testicular germ cell tumors, and male breast cancer." (PMID 38397209, 2024). "In the absence of BRCA1/2 germline mutations, alterations in other specific homologous recombination (HR) genes, such as PALB2, CHEK2, ATM, and NBN, can lead to an increased risk of breast cancer development." (PMID 39272660, 2024). "Among the significant hits are previously reported associations, including association between the number of putatively damaged copies of BRCA2 (p = 6.16 × 10−15) and CHEK2 (p = 3.34 × 10−15) and breast cancer." (PMID 38944039, 2024). "In patients with breast cancer, a high incidence of pathogenic variants of BRCA1 and BRCA2 is observed, as well as other highly mutated genes, such as PALB2, CHEK2, MUTYH, and ATM." (PMID 39335183, 2024). "Germline variants in CHEK2 have been linked to multi-organ cancer predisposition, and CHEK2 is now typically included with BRCA1, BRCA2, and PALB2 as a breast cancer risk gene." (PMID 39642869, 2024). "There are also multiple DNA repair genes that interact with the BRCA genes such as ATM, CHEK2, and BRIP1 that further increase the risk of breast cancer when mutated." (PMID 38927753, 2024). "The CHEK2 p.H371Y mutation, located in the kinase domain, results in reduced kinase activity in functional assays [PMID: 21618645] and is associated with breast cancer [PMID: 24390236]." (PMID 39411129, 2024). "By age 80, the cumulative risk of breast cancer was 30% (95% CI 16% to 41%) for ATM PTV carriers and 25% (19% to 30%) for CHEK2 PTV carriers, compared with 12% in the general population." (PMID 39209703, 2024). "The predictability of breast cancer by CHEK2 GPV carrier status (either 1100delC or I157T) and family history of breast cancer was determined using a logistic regression model." (PMID 39062660, 2024). "BC that is linked withgerminal mutations in BRCA1 has a triple negative phenotype(70–85 %), while ER-positive cases can be detected in carriersof mutations in the BRCA2, ATM, CHEK2 and PALB2 genes." (PMID 39027127, 2024). "While BRCA1 and BRCA2 remain the most well-known high-penetrance genes, others, such as ATM, BARD1, CHEK2, PALB2, RAD51C, and RAD51D, are now recognized as conferring moderate to high risk for breast cancer." (PMID 39590369, 2024). "FDA-approved therapies specific to breast cancer include Olaparib, which has demonstrated clinical efficacy for patients with ATM, BRCA1/2, and CHEK2 mutations, as well as alpelisib for patients with PIK3CA mutations." (PMID 38927753, 2024). "In the pedigree of patient 2469, who was diagnosed with breast cancer at 35 and carries the CHEK2 p.Gly167Arg a likely PV, we see numerous malignancies on the father’s side." (PMID 39624521, 2024).